EIF4A3 (eukaryotic translation initiation factor 4A3)
Diseases named in the same sentence as EIF4A3 in open-access papers (continued):
Sharing a sentence is not in itself a finding about the gene and the disease.
prostate carcinoma (9 papers, 2011 to 2025). A carcinoma that arises from epithelial cells of the prostate gland. "Collectively, these results suggest that functions and targeting of EIF4A3 should be further explored as a potential therapeutic avenue in prostate cancer." (PMID 37591798, 2023). "In conclusion, the current study identified potential novel biomarkers for prostate cancer development and/or progression such as eIF4A3, DDAH1, ARG2, Prdx3, and Prdx4 from proteomic data using systems biology approach." (PMID 21347291, 2011). "In addition, EIF4A3 was found highly expressed in many cancers, such as prostate cancer, bladder cancer, endometrial cancer, so EIF4A3 may be an oncogene in cancer." (PMID 39868374, 2024). "With siRNA screens, several of these were indicated in survival (DDX6, EIF4A3, PABPN1), growth (e.g., EIF5A, HNRNPH2, LRRC47, and NVL), and migration (e.g., NOL3 and SLTM) of prostate cancer cells." (PMID 37591798, 2023). "Protein network analysis and clustering of differentially expressed proteins revealed new targets such as DDAH1, ARG2, EIF4A3, Par4, PPA2, Prdx3 and Prdx4, which need further validation to define their potential application in clinical relevance in prostate cancer." (PMID 21347291, 2011).
pancreatic cancer (7 papers, 2009 to 2024). "EIF4A3 antigen and antibodies might be useful serum markers in pancreatic cancer diagnosis, as they are more strongly expressed in most pancreatic cancer tissues than in normal tissues." (PMID 34458150, 2021). "In pancreatic cancer, LINC01232 modulates TM9SF2 mRNA stability via recruiting EIF4A3." (PMID 37940881, 2023).
microcephaly (6 papers, 2016 to 2023). A congenital or acquired developmental disorder in which the circumference of the head is smaller than normal for the person's age and sex. "In mice, it has been demonstrated that haploinsufficiency in Magoh, Rbm8a, or Eif4a3 is sufficient to cause microcephaly in mice, indicating that these components are necessary in neurogenesis." (PMID 35406756, 2022). "Using a new conditional allele, we first show that Eif4a3 haploinsufficiency phenocopies aberrant neurogenesis and microcephaly of Magoh and Rbm8a mutant mice." (PMID 27618312, 2016). "Both Eif4a3 and Rbm8a haploinsufficiency caused severe microcephaly, with an average 70% reduction in cortical area of whole mount brains." (PMID 27618312, 2016). "While these studies show Magoh and Rbm8a are essential for corticogenesis, it remains unknown if impairment of the third major EJC constituent, Eif4a3, causes microcephaly." (PMID 27618312, 2016). "These defects lead to impaired cortical development and microcephaly, a phenotype also associated with RBM8A and EIF4A3 mutations in humans." (PMID 32502192, 2020). "The neural cell death phenotype is similar to that seen in mouse heterozygous EJC mutant embryos, and is consistent with the microcephaly phenotype in human patients heterozygous for hypomorphic RBM8A and EIF4A3 mutations." (PMID 32502192, 2020). "While knockout of Upf1 and other NMD factors is embryonic lethal in mice, mice haploinsufficient for the EJC components Magoh, Rbm8a, and Eif4a3 exhibit aberrant neurogenesis and microcephaly (20, –, 22)." (PMID 30401782, 2018). "The microcephaly phenotype of Rbm8a and Eif4a3 mutant mice was significantly worse than Magoh haploinsufficient mice, which exhibited a 40% reduction." (PMID 27618312, 2016). "First, we generated a NSC-specific conditional Eif4a3 mouse model to demonstrate that Eif4a3 haploinsufficiency phenocopies the aberrant neurogenesis and microcephaly seen in Rbm8a and Magoh mutants." (PMID 27618312, 2016). "However, mice haploinsufficient for NMD factors upstream of UPF1, including Magoh, Rbm8a, and Eif4a3, develop microcephaly (20, –, 22)." (PMID 30401782, 2018). "To understand whether common mechanisms contribute to microcephaly following depletion of EJC core components, we first sought to address the role of the third core EJC component, Eif4a3, in brain development." (PMID 27618312, 2016).
bladder cancer (5 papers, 2023 to 2025). "Our team aims to investigate the association between EIF4A3 and tumor progression and immune microenvironments to determine its potential as a biomarker for human cancers, particularly bladder cancer." (PMID 37777564, 2023). "In this study, we validated that EIF4A3 is upregulated in bladder cancer and higher expression of EIF4A3 was significantly associated with a poorer outcome in bladder cancer patients." (PMID 37777564, 2023). "Although EIF4A3 has been shown to be upregulated in bladder cancer and associated with poor outcomes in patients, its prognostic value and role in immunity across various human cancers remains unclear." (PMID 37777564, 2023). "In bladder cancer (BCa) tissues and cell lines, eukaryotic translation initiation factor 4A3 (EIF4A3) promotes the upregulation of circ0008399 expression and inhibits apoptosis in BCa cells." (PMID 40458727, 2025). "Particularly in bladder cancer, EIF4A3 was correlated with all m6A related genes, suggesting its potentially comprehensive role to regulate gene fate as m6A suppressor." (PMID 37777564, 2023). "In contrast to previous research, our study utilized bladder cancer and para-cancer tissues with clinical data analysis to validate the prognostic role of EIF4A3 in bladder cancer." (PMID 37777564, 2023). "Subsequent validation experiments confirmed that bladder cancer patients exhibiting higher levels of EIF4A3 expression have significantly worse prognostic outcomes." (PMID 37777564, 2023). "To verify the expression level of EIF4A3 and its prognostic value, we collected 62 bladder cancer tissue samples and 12 adjacent para-cancer tissues along with clinical data." (PMID 37777564, 2023). "Our study unveiled a considerable increase in the expression levels of EIF4A3 in bladder cancer compared to para-cancer tissue." (PMID 37777564, 2023). "Overall, the expression level of nucleus EIF4A3 was significantly higher in bladder cancer tissues compared to adjacent para-tumor tissues." (PMID 37777564, 2023). "Our results confirmed that the upregulation of EIF4A3 occurs in bladder cancer, and that patients with increased expression levels of EIF4A3 exhibit a poorer prognosis." (PMID 37777564, 2023). "We confirmed that the expression level of EIF4A3 is significantly higher in bladder cancer than para-cancer tissaue." (PMID 37777564, 2023). "We initially investigated the expression and prognostic impact of EIF4A3 in bladder cancer." (PMID 37777564, 2023). "Similarly, in bladder cancer EIF4A3 was significantly upregulated and related to poor prognosis; knockdown of EIF4A3 significantly inhibited bladder cancer cell proliferation and promoted cell apoptosis." (PMID 37777564, 2023). "Additionally, Kaplan–Meier survival analysis demonstrated that the upregulation of both nucleus and cytoplasmic EIF4A3 expression levels was significantly correlated with a poorer overall survival rate in bladder cancer." (PMID 37777564, 2023). "We analyzed the expression levels of EIF4A3 in bladder cancer compared to para-cancer tissue." (PMID 37777564, 2023). "Moreover, paired bladder cancer samples (from the same patient) mRNA expression data from TCGA also revealed a significantly high EIF4A3 expression in tumor tissues (p < 0.001)." (PMID 37180585, 2023). "The results revealed a significant correlation that expression of EIF4A3 in the cytoplasm (HR = 17.829, 95% CI 2.300–138.173, P = 0.006) and TNM stage (HR = 2.190, 95% CI 1.002–4.786, P = 0.049) was significantly related with the risk of death from bladder cancer." (PMID 37777564, 2023). "EIF4A3 (Eukaryotic translation initiation factor 4A3 (EIF4A3) was recently recognized as an oncogene; however, its role in BLCA (bladder cancer) remains unclear." (PMID 37180585, 2023).
glioma (5 papers, 2020 to 2024). A benign or malignant brain and spinal cord tumor that arises from glial cells (astrocytes, oligodendrocytes, ependymal cells). "In gliomas, eIF4A3 induces the expression of circASAP1, which promotes malignant progression and resistance to temozolomide." (PMID 39085875, 2024). "We analyzed the expression differences of eIF4A3 in nontumor tissues and glioma tissues of various grades and analyzed the relationship between eIF4A3 expression and glioma prognosis in the TCGA dataset." (PMID 35677890, 2022). "The tissue samples obtained from gliomas of various grades were immunostained to analyze the eIF4A3 expression levels." (PMID 35677890, 2022). "Moreover, analysis of the CGGA, TCGA and the GSE4290 dataset indicated that EIF4A3 expression was moderately increased in lower-grade glioma (LGG) tissues but strongly elevated in GBM tissues." (PMID 36755314, 2023). "It was found that the higher the grade of glioma, the higher the expression of eIF4A3." (PMID 35677890, 2022). "In addition, elevated EIF4A3 expression was identified in samples of relapsed glioma compared to samples of non-relapsed glioma, and a positive correlation between circCABIN1 and EIF4A3 expression was identified in glioma samples." (PMID 36755314, 2023). "Furthermore, eIF4A3 was rare in glioma of grade 1 but abundantly expressed in gliomas of grade 4." (PMID 35677890, 2022). "Additionally, the expression of eIF4A3 increased with the increasing grade of glioma." (PMID 35677890, 2022). "CircCABIN1 could be cyclized by eukaryotic translation initiation factor 4A3 (EIF4A3) and is highly expressed in GBM tissues and glioma stem cells (GSCs)." (PMID 36755314, 2023). "The level of eIF4A3 in glioma was significantly higher than that in nontumor tissue, and the level of eIF4A3 increased with the grade of glioma." (PMID 35677890, 2022). "Twenty-two vital RBPs, IGF2BP1, IGF2BP3, EIF4A3, hnRNPC, and AGO2, can bind to circRNAs and may play important biological functions in glioma." (PMID 33323543, 2020). "It was also found that eIF4A3 is expressed at low level in LGG and high level in HGG in tissue specimens of gliomas, which suggests that eIF4A3 may be related to the malignant behavior of gliomas." (PMID 35677890, 2022). "However, the expression of eIF4A3 had no obvious effect on the prognosis of glioma patients, which may be related to the poor prognosis of glioma patients." (PMID 35677890, 2022). "In conclusion, our study elucidates the regulatory mechanism that circ_0055412 regulated EIF4A3/CAPG axis and miR‐330‐3p/NFATC3/Wnt/β‐catenin pathway to promote cisplatin resistance of glioma cells, which might provide the theoretical and practical basis for glioma therapy." (PMID 35332692, 2022).
melanoma (5 papers, 2022 to 2024). A malignant, usually aggressive tumor composed of atypical, neoplastic melanocytes. "Knockdown of circRNA hsa_circ_0062270 suppressed melanoma tumor growth in vivo by inhibiting RBP EIF4A3 expression." (PMID 36065311, 2022).
non-small cell lung carcinoma (5 papers, 2021 to 2025). A group of at least three distinct histological types of lung cancer, including non-small cell squamous cell carcinoma, adenocarcinoma, and large cell carcinoma. "LINC00667 promotes non-small cell lung cancer (NSCLC) angiogenesis through EIF4A3-mediated stabilization of VEGFA." (PMID 37940881, 2023). "Furthermore, circular RNA CircTADA2A has been reported to enhance MAPK8 expression by acting as a miR-214-3p sponge and an EIF4A3 decoy, thereby promoting invasion and migration in non-small cell lung cancer cells." (PMID 41318488, 2025). "In addition, EIF4A3 is overexpressed in non-small cell lung cancer (NSCLC), where it competitively binds to LINC00667 and thereby upregulates expression of its target gene encoding vascular endothelial growth factor A (VEGFA)." (PMID 34458150, 2021).
cholangiocarcinoma (4 papers, 2021 to 2025). A carcinoma that arises from the intrahepatic biliary tree (intrahepatic cholangiocarcinoma) or from the junction, or adjacent to the junction, of the right and left hepatic ducts (hilar cholangiocarcinoma). "Further analysis of the GEPIA database in conjunction with western blot analyses unveiled revealed EIF4A3 expression levels in cholangiocarcinoma tissues and ICC cells." (PMID 39836545, 2025). "Overall, YY1/eIF4A3/circ-ZNF609/miR-432-5p/LRRC1 have a significant role in progression of cholangiocarcinoma, and circ-ZNF609 is expected to become a novel biomarker for targeted therapy and prognosis evaluation of cholangiocarcinoma." (PMID 34898474, 2021).
colon cancer (3 papers, 2021 to 2023). "The binding of eIF4A3 to LncRNA H19 prevents the recruitment of eIF4A3 to the mRNAs of the cell cycle regulators, including cyclin D1 and cyclin E1, for post-transcriptional modification, resulting in an acceleration of colon cancer cell growth." (PMID 34207140, 2021).
liver cancer (3 papers, 2021 to 2023). An epithelial or non-epithelial malignant neoplasm that arises from the liver. "In liver cancer, EIF4A3 has been found to induce dysfunction of CD8+T cells by promoting the formation of circCCAR1, leading to the development of resistance mechanisms against PD-1 inhibitors in tumor cells." (PMID 37777564, 2023). "Consistently, the three liver cancer cell lines studied here exhibited considerable EIF4A3 expression at mRNA and protein levels and were able to release it." (PMID 36419260, 2022). "As a proof‐of‐concept, the forced overexpression of EIF4A3 increased the tumourigenic properties of liver cancer cells, demonstrating the implication of EIF4A3 in HCC biology." (PMID 36419260, 2022). "A pan-cancer assessment of eIF4A3 expression indicated that it was upregulated in many cancers, including liver cancer." (PMID 34367948, 2021). "To further validate this idea and to explore the putative utility of blocking EIF4A3 and FGFR4 simultaneously in liver cancer cells, we performed functional assays in response to EIF4A3‐silencing alone or in combination with a specific FGFR4‐inhibitor (BLU9931 or BLU)." (PMID 36419260, 2022). "This study also demonstrates that EIF4A3 can control tumourigenic capacity of liver cancer cells in vitro and the in vivo tumour growth in a preclinical HCC model of Hep3B‐induced xenografts by the alteration of the expression and splicing events of key oncogenes such as FGFR4." (PMID 36419260, 2022). "In addition, the beta value for eIF4A3 promoter methylation was lower for liver cancer than for normal tissue." (PMID 34367948, 2021).
viral infection (3 papers, 2019 to 2026). "This suggested that eIF4A3 was also essential for the biogenesis of circHOMER1 after viral infection." (PMID 40662732, 2025). "Given the established role of RBP eIF4A3 in neuronal circHOMER1 biogenesis, we hypothesized its involvement in the increased expression of circHOMER1 after viral infection." (PMID 40662732, 2025). "We next sought to determine whether eIF4A3 was also critical for the biogenesis of circHOMER1 upon viral infection." (PMID 40662732, 2025). "In summary, we describe that by employing a novel PB2-tagging approach, we identified influenza PB2-interacting partners during virus infection, and we demonstrated that host factor eIF4A3 works as a binding protein of the AIV ribonucleoprotein complexes in mammalian cells." (PMID 31379779, 2019). "Importantly, eIF4A3 played a similar role in PVY and TuMV infection: transgenic expression of eIF4A3 in Nicotiana benthamiana significantly enhanced viral infection." (PMID 41505092, 2026).
Cirrhosis (2 papers, 2021 to 2022). A chronic disorder of the liver in which liver tissue becomes scarred and is partially replaced by regenerative nodules and fibrotic tissue resulting in loss of liver function. "To investigate the diagnostic capacity of EIF4A3 in plasma samples, we evaluated EIF4A3 levels in patients with NAFLD, cirrhosis and HCC, as well as control individuals (Prospective‐1 cohort)." (PMID 36419260, 2022).
diabetes (2 papers, 2021 to 2023). "It was also reported that EIF4A3 can regulate cell cycle and apoptosis through TNF-α/NF-ĸB signaling pathway, which is one of the key signal pathways affecting diabetes." (PMID 35046894, 2021).
meningioma (2 papers, 2024 to 2025). A generally slow growing tumor attached to the dura mater. "Loss-of-function experiments revealed that silencing EIF4A3 markedly repressed the proliferation, metastasis, and immune escape of meningioma cells in vitro, and promoted the immunosuppressive TME formation." (PMID 38771413, 2024). "In conclusion, our study revealed that hsa_circ_0004872 plays a pivotal role in mitigating the proliferation, metastasis, and immune escape of meningioma cells through its interaction with the EIF4A3/PD-L1 axis." (PMID 38771413, 2024). "As expected, our experiments, for the first time, discovered that EIF4A3 was significantly upregulated in meningioma tissues and cells, and had a positive correlation with PD-L1." (PMID 38771413, 2024). "LDH assay revealed that knockdown of EIF4A3 promoted LDH production in meningioma cells, suggesting that the cytotoxicity of CD8+ T cells was enhanced." (PMID 38771413, 2024). "Inhibition of EIF4A3 improved immune escape, proliferation, and metastasis of meningioma cells." (PMID 40739089, 2025). "In this section, we investigated the detailed roles of EIF4A3 in meningioma." (PMID 38771413, 2024). "EIF4A3 upregulation facilitated the metastasis and immune escape of meningioma cells." (PMID 38771413, 2024). "Therefore, we hypothesized that hsa_circ_0004872 could target the EIF4A3/PD-L1 axis to regulate the proliferation, metastasis, and immune escape of meningioma cells." (PMID 38771413, 2024). "Furthermore, RT-qPCR assay suggested the higher EIF4A3 mRNA expression in meningioma tissues than that in non-cancerous tissues." (PMID 38771413, 2024).
pancreatic adenocarcinoma (2 papers, 2021). "Another study found that EIF4A3 is recruited by LINC01232 to stabilize transmembrane 9 superfamily member 2 (TM9SF2) mRNA and regulate its expression, thereby contributing to pancreatic adenocarcinoma (PAAD)." (PMID 34458150, 2021).
selenium deficiency (2 papers, 2016 to 2021). A nutritional deficiency disease resulting from inadequate selenium levels in the body, which can lead to impaired function of selenoproteins essential for antioxidant defense and thyroid hormone metabolism. "During selenium deficiency, expression of eIF4a3 is upregulated several fold and binds to a variable extent to type 1 SECIS elements preventing, where tested, Sec insertion." (PMID 27881738, 2016). "In particular, during selenium deficiency, EIF4A3 is upregulated, potentially at the post-transcriptional level, but the exact mechanism is unknown." (PMID 34458150, 2021).
acute myocardial infarction (1 paper, 2022). Necrosis of the myocardium, as a result of interruption of the blood supply to the area. "Studies have shown that EIF4A3 is associated with acute myocardial infarction, and knockout of EIF4A3 can lead to failure of heart looping." (PMID 35207515, 2022).